EGFR (epidermal growth factor receptor)
Diseases named in the same sentence as EGFR in open-access papers (continued):
Sharing a sentence is not in itself a finding about the gene and the disease.
breast tumors (283 papers, 1991 to 2026). "These alterations occur at rates such as those seen with epidermal growth factor receptor (EGFR) mutations, a commonly occurring mutation, at frequencies between 3% and 5% of all breast tumors." (PMID 40614729, 2025). "Kaplan–Meier survival plots indicated that CCR7- and EGFR-expressing breast tumors were associated with a shorter survival time compared to patients expressing low levels of the receptors." (PMID 35203305, 2022). "Kaplan–Meier analyses demonstrate that breast tumors with high expression of both EGFR and MYC are likewise associated with decreased patient survival." (PMID 31839995, 2019). "Immunohistochemical analysis of IKKε expression in our cohort of primary breast tumors revealed an unexpected inverse association with lymph node metastasis and a positive association with EGFR status." (PMID 28532474, 2017). "High expression of EGFR is characteristic of ER− breast tumors and has been linked to poor prognosis." (PMID 26840086, 2016). "Consistent with a potential role for EGFR in HER2Δ16 tumorigenesis, coexpression of EGFR in breast tumors with activated HER2 is associated with significantly shorter patient survival than patients with tumor expression of activated HER2 or EGFR alone." (PMID 25532106, 2014). "The stratification of breast tumors according to their biological subtypes suggests that the apparently protective effects of EGFR polymorphisms are characteristic of luminal A tumors." (PMID 24629097, 2014). "For example, the length of a polymorphic [GT/CA] allele within intron one of the EGFR gene is inversely correlated with transcription, and EGFR expression is increased in breast tumors with [GT/CA]15 alleles, relative to tumors with [GT/CA]18 alleles." (PMID 23450065, 2013). "EGFR is overexpressed in human breast tumors and the EGFR signaling pathway is implicated in the control of cell survival, proliferation, angiogenesis and metastasis." (PMID 21738726, 2011). "Lung metastases as the first distant site were strongly associated with breast tumor EGFR expression." (PMID 21914172, 2011). "Approximately 30% of human breast tumors overexpress EGFR, and this overexpression correlates with a loss of estrogen responsiveness and a poor prognosis." (PMID 20624308, 2010). "Except for one EGFR mutation (Case #13), the same somatic mutations were observed in the brain metastases with similar MAPs as in the matched primary breast tumors." (PMID 20604919, 2010). "We aimed to study the mutation frequency of KRAS in that subtype of breast tumors to provide a molecular basis for the evaluation of anti-EGFR therapies." (PMID 20385028, 2010). "An EGFR-associated signature was developed in vitro, evaluated on 241 primary breast tumors; three distinct clusters of genes were evident in vivo, two of which were predictive of poor patient outcomes." (PMID 17663798, 2007). "It is possible that the rapid effects of steroid hormones leading to sustained proliferation or survival of breast tumor cells proceed by establishing an autocrine loop of EGFR activity that is linked, in part, to Wnt1 production." (PMID 17897439, 2007). "EGFR and ErbB2 co-overexpression in breast tumors is associated with resistance to endocrine therapies (and references therein)." (PMID 16371159, 2005). "In this study, we have shown that moderate to high levels of EGFR phosphorylation (Y1086) were observed in 67 out of 89 (75.3%) primary breast tumours and was associated with invasive breast tumours (P<0.05)." (PMID 16288304, 2005). "Interestingly, a naturally occuring constitutively active variant of EGFR with an in-frame 801 bp deletion excising most of the extracellular domain has been found in primary breast tumours." (PMID 25969993, 2015).
breast tumors (continued). "The stratification of breast tumors according to their biological classification indicates that the association between combined variant EGFR polymorphisms and better lymph node status occurs for tumors classified as luminal A, but not for the other biological subtypes." (PMID 24629097, 2014). "In addition, EGFR is linked to higher mitotic rate and a shorter relapse free interval and survival and triple negative and basal-like breast tumors." (PMID 25417118, 2014). "Although KRAS is mutated in only a minor fraction of breast tumors (5%), about 60% of the basal-like subtype express EGFR and, therefore could be targeted by EGFR inhibitors." (PMID 20385028, 2010). "Met has been implicated in the pathogenesis of breast tumors and therefore may cooperate with EGFR for tumor growth." (PMID 20624308, 2010). "Furthermore, higher Jab1 nuclear expression was associated with EGFR+ status in a cohort of ERα- breast tumors, and this relationship was most significant in tumors that expressed both EGFR and S100A7 markers." (PMID 18534028, 2008). "In certain cases, targeting direct activators such as TBL2 and PRMT5 has been explored as a potential therapeutic strategy for breast tumors, or even the complete inhibition of EGFR/PI3K/AKT and mTOR mediated pathways using natural compounds." (PMID 39950162, 2025). "They found that the effect of PA-MSHA on breast tumors is mannose-dependent, or, in other words, the bacterium uses sugar-binding properties of cancer cells and triggers the inactivation of the EGFR signaling pathway." (PMID 38339275, 2024). "Our findings identify miR-770-5p as a tumor suppressor in breast tumors, acting as a regulatory switch that targets key players such as EGFR, HER2, IGF1R, as well as downstream effectors including AKT, ERK, and mTOR." (PMID 39051060, 2024). "Here, sialic acid removal by STi also enhanced human IgG1 and IgG2 mediated ADCP of HER2 and EGFR positive breast tumor cells." (PMID 39659795, 2024). "Tanshinlactone as a novel therapeutic agent, is capable of selectively inhibiting ER+ and HER2+/EGFR + breast tumors through a unique mechanism of inducing catastrophic macropinocytosis." (PMID 39906392, 2024). "We show that removal of α2,3 linked sialic acids resulted in enhanced neutrophil cytotoxicity in vitro in the presence of human IgG1 and IgG2 antibodies against HER2 and EGFR positive breast tumor cells." (PMID 37346044, 2023). "The exosome harboring EGFR aptamer-loaded siSurvivin NPs (EGFRapt/Exosome/siSurvivin) inhibited breast tumor in MDA-MB-468 cells orthotopic xenograft breast tumor bearing mice." (PMID 36678782, 2023). "Gold NPs modified with trimethyl chitosan (TMC) were developed as efficient delivery carriers to enhance the stability and cellular uptake of siRNA targeting EGFR in breast tumors." (PMID 36678782, 2023). "It has been also established that PTPN9 stimulated the dephosphorylation of EGFR and ErbB2 in breast tumor cells." (PMID 35156900, 2022). "EGFR is one of the most well-studied signaling pathways that contributes to the invasion, dissemination, and metastasis of breast tumors." (PMID 35414113, 2022). "EGFR overexpression in breast tumours can be high, varying in intensity in different tumour subtypes." (PMID 36158981, 2022). "Overexpression of EGFR and HER2 occurs in various human tumors, including prostate, brain, lung, and breast tumors, and is implicated in tumor development." (PMID 36713381, 2022). "New therapies, new antibody formations or new associations with TKIs signal the importance of adequately measuring EGFR, both as a prognostic biomarker, and as a treatment predictor, in women with TN breast tumours." (PMID 36158981, 2022). "In 1998, when the FDA approved Herceptin (anti-EGFR mAb for EGFR+ breast tumors) and HerceptTest (to detect such tumors), it became the first “official” CMDx invented." (PMID 35563034, 2022).
breast tumors (continued). "SA analysis of 747 breast tumors from the TCGA dataset suggested that ~30% of TNBC tumors should benefit from anti-EGFR inhibitors." (PMID 34638492, 2021). "Recently, disulfide bond-disrupting agents (DDAs), including RBF3 and tcyDTDO, have been shown to kill breast tumors with acquired resistance to epidermal growth factor receptor (EGFR)/human epidermal growth factor receptor 2 (HER2) tyrosine kinase inhibitors." (PMID 34300195, 2021). "Given the important role of tumor-cells–macrophages interaction on tumor growth, Phillip and colleagues investigated the STAT3 activators and EGFR agonists secreted by tumor-primed monocytes and MΦ and their impact on breast tumor growth." (PMID 34207035, 2021). "Researchers showed that exosomes delivered miRNA efficiently to EGFR-expressing breast tumor cells in a mouse study." (PMID 33375558, 2020). "We observed a different pattern in breast tumors that metastasize to lung and harbor a mutation in KEAP1, KRAS, STK11, or EGFR." (PMID 32374727, 2020). "For breast tumors, synergy with HER2-Neu/EGFR inhibitors correlated significantly with HER2-Neu/EGFR-activating mutations (P = 1 × 10−4)." (PMID 32523045, 2020). "The ex vivo and in vivo cytotoxicity analysis of micelles showed the effective targeted and hindered EGFR-overexpressing on MDA-MB-231 TNBC breast tumor cell lines." (PMID 33333778, 2020). "This question was brought up by our recent observation that breast tumor uptake of FDG in human patients was strongly influenced by EGFR status." (PMID 31532771, 2019). "Our group recently discovered that breast tumor FDG uptake is more strongly influenced by EGFR status than by other major biomarkers." (PMID 31532771, 2019). "Signaling from EGFR also represents a major mechanism through which breast tumors that are initially responsive to endocrine therapy acquire resistance." (PMID 31532771, 2019). "Consistent with in vitro results, UNC5A expression negatively correlated with EGFR expression in breast tumors, and lower expression of UNC5A, particularly in ERα+/PR+/HER2− tumors, was associated with poor outcome." (PMID 29720215, 2018). "Human epidermal growth factor receptor HER3 (ErbB3), especially in association with its relative HER2 (ErbB2), is known as a key oncogene in breast tumour biology." (PMID 30367623, 2018). "For instance EGFR-specific binding peptide GE11 can lead let-7a-containing exosomes to EGFR-positive cancer cells, that considerably suppressed EGFR-positive human breast tumor cell development in a heterograft mouse model." (PMID 29868251, 2018). "Both observations advocate additional studies, including larger scale IHC profiling of primary breast tumors, to determine the functional relationship between EGFR and IKKε and importantly to clarify the role of IKKε in metastasis." (PMID 28532474, 2017). "EGFR promotes breast tumor growth and lung metastasis by HIF1α repression of miR-338-3p and subsequent activation of EYA2." (PMID 28703807, 2017). "Similar to EGFR, c-Src is also overexpressed in many types of cancer and has been shown to be co-overexpressed with EGFR in a subset of breast tumors." (PMID 29132432, 2017). "The mRNA levels of ERalpha, ERbeta, epidermal growth factor receptor, ErbB2, ErbB3, ErbB4, ERRα, ERRβ, and ERRγ were determined in unselected primary breast tumors and normal mammary epithelial cells enriched from reduction mammoplasties." (PMID 28945747, 2017). "Engineered bacteria were administered to mice implanted with mouse colon or breast tumor cells expressing high level of EGFR." (PMID 28473665, 2017). "This knowledge will help determine if therapeutic strategies targeting IKKε are relevant for IKKε+/EGFR+ breast tumors." (PMID 28532474, 2017). "Previous experimental and clinical studies have indicated that EGFR based signalling in ER+ breast tumors leads to resistance to hormone therapy through hormone independent proliferation of tumors." (PMID 29190299, 2017).
breast tumors (continued). "Here, we show that EGFR promotes breast tumor growth and metastasis by downregulating the tumor suppressor micoRNA-338-3p (miR-338-3p) and activating the EYA2 (EYA transcriptional coactivator and phosphatase 2) oncoprotein." (PMID 28703807, 2017). "Lapatinib (Tykerb) is a dual epidermal growth factor receptor (EGFR)/human EGFR-2 (HER2) tyrosine kinase inhibitor (TKI) approved for patients with HER2-amplified breast tumours presenting with metastatic lesions." (PMID 27402251, 2016). "Breast tumors expressing EGFR presented higher proliferation rates and were more likely to be grade III and estrogen receptor negative." (PMID 27055285, 2016). "In contrast to HER2 but consistent with our in vitro data, EGFR protein expression in breast tumors positively correlated with CD47 mRNA expression (p= 0.009)." (PMID 26840086, 2016). "Most of the basal like breast tumors express or over-express EGFR and have a high propensity for metastasis." (PMID 25940703, 2015). "For example, CDH3 was significantly up-regulated in the stromals of both breast and prostate tumors, however EGFR was only significantly down-regulated in the stromal of breast tumor." (PMID 25826086, 2015). "The activation of the neurotensinergic system in breast tumors induces the overexpression of the EGFR, HER2 and HER3 receptors and their concomitant autocrine activation." (PMID 25249538, 2014). "The relationship between EGFR mRNA expression levels and (CA)n genotypes or prognostic categories of breast tumors were explored." (PMID 24629097, 2014). "A study has reported that ω-3 fatty acids, such as DHA and EPA, modified the lipid composition of membrane and altered EGFR and p38 signaling pathways in breast tumor cells." (PMID 24987192, 2014). "While surprising, similar effects have been observed in breast tumor cells grown in three-dimensional reconstituted basement membrane, where EGFR overexpression has been found to trigger compensatory α1 integrin upregulation." (PMID 25000176, 2014). "More recent data indicated that in addition to CXCR4 and CCR7 and its ligands also EGFR was significantly higher expressed in breast tumor cells with lymph node metastasis, which was correlated to shorter survival period of afflicted patients." (PMID 23667660, 2013). "Further, in addition to the subcutaneous implantation, we utilize syngeneic orthotopic implantation model to investigate the role of D-RF6 CPPP in suppresses breast tumor growth especially the therapeutic effect against EGFR TKI-resistant TNBC." (PMID 23593472, 2013). "This study showed that the uptake of [11C]PD153035 was correlated with EGFR expression in breast tumors." (PMID 23533377, 2013). "Phospho-tyrosine (active) kinase antibody array analyses on breast and breast tumor tissues revealed that the activities of both EGFR (Her1) and Her2 were enhanced about 7.5-fold in the TGFα transgenic mice relative to the non-transgenic controls." (PMID 24279986, 2013). "Modified tyrosine kinase inhibitor, [11C]-4-N-(3-bromoanilino)-6,7-dimethoxyquinazoline ([11C]PD153035), has been evaluated as a PET agent to measure EGFR expression in breast tumors." (PMID 23533377, 2013). "To confirm the EGFR quantification, we extracted total RNA from each breast tumor for RT-qPCR analysis." (PMID 22829865, 2012). "This percentage of NuclErbB-2 staining is comparable to the one (38%) reported in breast tumors for nuclear expression of the epidermal growth factor receptor (EGF-R), another member of the ErbBs family." (PMID 22356700, 2012). "Our results show that breast tumors with elevated levels of EGFR or HER2 are more likely to express dimers." (PMID 22829865, 2012). "Hochgrafe and colleagues found that Met is phosphorylated in breast tumors and that the phosphorylation of EGFR and Met is enriched in TNBC tumors." (PMID 22788954, 2012).
breast tumors (continued). "For instance, an increased expression and/or activation of growth factor receptors, such as EGFR/HER2, have been associated with the failure of endocrine therapy in breast tumors." (PMID 22251451, 2012). "Our studies confirm that while erlotinib prevents the emergence of TNBCs, manifest breast tumors grow independently of EGFR signaling." (PMID 21396117, 2011). "Our aim is to apply the assay to assess EGFR/HER2 dimerization in HER2 positive breast tumors as well as EGFR over-expressing tumors like HNSCC." (PMID 21908901, 2011). "We report the first quantitative and qualitative analysis of the poly (A)+ transcriptome of two human mammary cell lines, differentially expressing (human epidermal growth factor receptor) an oncogene over-expressed in approximately 25% of human breast tumors." (PMID 21731642, 2011). "Despite strong correlative evidence from human breast tumors, transgenic mouse models have clearly demonstrated that overexpression of the EGFR alone is insufficient for tumor formation." (PMID 20624308, 2010). "One such inhibitor, INCB7839, has been shown to cooperate with receptor tyrosine kinase inhibitors that target EGFR and ErbB2 to impair breast tumor growth." (PMID 20711474, 2010). "EGFR and ErbB2 receptor over-expression occurs in one quarter to one-half of all breast tumors, and this correlates with a significantly decreased disease-free and overall survival rates." (PMID 18597688, 2008). "Analysis of EGFR and Jab1 expression in a cohort of invasive breast tumors by tissue microarray and immunohistochemistry confirmed a relationship between EGFR and increased nuclear Jab1 within the ERα- subset (n = 154, P = 0.019)." (PMID 18534028, 2008). "Breast tumours belonging to these subclasses more often demonstrate respectively EGFR and ErbB2 overexpression." (PMID 17700572, 2007). "Consistent with these preclinical developments, we found that YB-1 is strongly correlated with EGFR in primary breast tumours by screening a tissue microarray of ~490 cases." (PMID 17875215, 2007). "The classification of the breast tumour samples into the different cell-of-origin subtypes was in close agreement with IHC staining results obtained for ER, PR, ErbB2, EGFR and CK5/6, thereby validating our classification." (PMID 17848951, 2007). "Out of 19 ER+ breast tumours 15 showed no overexpression of EGFR and/or ErbB2 whereas 10 out of 18 ER− breast tumours showed overexpression of EGFR and/or ErbB2 (κ=−0.343, P=0.031)." (PMID 17700572, 2007). "Little EGF receptor (EGFR) activity was detected in normal or benign tumour tissues except for meningioma (positive in 95% samples), but EGFR were present in 43% of 131 breast tumours and 75% of 55 primary cerebral tumours." (PMID 2021539, 1991). "Indeed, phosphorylation of the T567 residue of EZRIN leads to its co-localization in a functional complex with NHE1, EGFR, and β1-integrin in human breast tumors, suggesting its crucial role as a scaffold protein of EGFR." (PMID 39937579, 2025). "Amplification at chromosome 7p11.2 (EGFR) can promote the invasion and metastasis of breast tumors." (PMID 37719859, 2023). "This could lead to the secretion of the EGFR, promoting migration and invasion of breast tumor cells." (PMID 37685910, 2023). "In addition, a reciprocal TNS3-TNS4 switch regulates the invasive capacity of breast tumors downstream of the EGFR via direct interaction with b1 integrins." (PMID 37510408, 2023). "Besides mAChR, another subtype α9 of nAChR, which interacts with ERBB2 and epidermal growth factor receptor, can also influence intercellular adhesion of breast tumor cells thus mediating the metastasis of breast tumor." (PMID 37773152, 2023). "Finally, the tumour regression capacity of SSNs and PEG-SSNs with loaded anti-EGFR siRNA and the safety profile of the formulations were evaluated in the same breast tumour-bearing mouse model." (PMID 36412852, 2022).